EGFR (epidermal growth factor receptor)
Diseases named in the same sentence as EGFR in open-access papers (continued):
Sharing a sentence is not in itself a finding about the gene and the disease.
paronychia (continued). "About 10 and 15% of patients experience paronychia during 4–8 weeks’ EGFR-TKIs treatment." (PMID 32179761, 2020). "However, the Osimertinib therapy subgroup exhibited a higher proportion of pruritus, diarrhea, dry skin, paronychia, and prolonged QT interval than the EGFR-TKIs/chemotherapy subgroup." (PMID 31651902, 2019). "Paronychia (painful inflammation of the nail fold) and periungual pyogenic-like lesions are the frequent adverse reaction to EGFR inhibitors, appearing after one or two months of treatment in 10-15% of the patients due to the direct inhibition of keratinocytes in the nail matrix." (PMID 27974909, 2016). "Tolerability of anti-EGFR agents is also important; afatinib had relatively high levels of treatment-related adverse events (diarrhoea: 95%, leading to discontinuation in 1% of patients; rash: 62% and paronychia: 57%)." (PMID 25100284, 2014). "Therapy with EGFR–TKIs has improved clinical outcomes, but they are accompanied by a number of adverse events that can be effectively managed, especially diarrhea, rash, mucositis, and paronychia." (PMID 25279350, 2014). "Cytotoxic anticancer agents and multikinase inhibitors (e.g., capecitabine, taxane, and regorafenib) may cause paronychia in addition to HFS; therefore, the frequency can be increased in regimens that involve the use of EGFR inhibitors with cytotoxic anticancer agents." (PMID 40888993, 2025). "Note that symptoms such as acneiform rash, xerosis, eczema, paronychia, changes in the nails, arthralgia, or stiffness of limb joints, which are common side effects of EGFR inhibitors or aromatase inhibitors, might be extracted as closely related expressions to those of HFS signals." (PMID 38625718, 2024). "This survival benefit was associated with a higher incidence of hematological and non-hematological AEs, other than paronychia/nail disorders, which usually occur after several weeks of treatment with anti-EGFR, particularly in association with fluoropyrimidines." (PMID 34778029, 2021). "Skin toxicity is one of the most prevalent AEs associated with EGFR-TKI treatment and could have varied manifestations including acneiform rash, dry skin, erythema, fissures and cracks, paronychia and pruritis, which are common and can be well tolerated upon using ointments and bandages." (PMID 32796633, 2020). "Cutaneous adverse reactions (CARs) are common complications of epidermal growth factor receptor (EGFR) inhibitor therapy, with papulopustular eruptions and paronychia being the most frequent." (PMID 40724845, 2025). "The most frequently observed adverse reactions during EGFR-TKI (afatinib and dacomitinib) therapy included skin rash/acneiform eruption, stomatitis/oral ulcer, diarrhea, paronychia, and pruritus." (PMID 38373960, 2024). "The most common AEs were EGFR TKI class-related toxicities (diarrhea, rash/acne, stomatitis, and paronychia) consistent with findings from the LUX-Lung 3, 6, and 7 studies." (PMID 34307179, 2021). "EGFR inhibitor-related skin toxicities are evaluated by the Common Terminology Criteria for Adverse Events (CTCAE) and Dermatology Life Quality Index, and in the case of paronychia, SPOT can be useful for evaluating how the symptoms affect the patient’s QOL." (PMID 40888993, 2025). "Age had no significant impact on the severity of anti-EGFR inhibitor-induced paronychia (p = 0.818)." (PMID 36980549, 2023). "From the EGFR exon20ins post platinum-based therapy cohort in the CHRYSALIS study, the most common adverse events include rash (86%), infusion-related reaction (65%), and paronychia (42%)." (PMID 37880647, 2023). "For example, the rash and paronychia incidence of afatinib, a second-generation EGFR-TKI, was recorded as high as 89.1% and 56.8%, while the corresponding data the first-generation EGFR-TKI (gefitinib and erlotinib) was generally lower (rash was 66.2% ~ 73% and paronychia was 4%—13.5%)." (PMID 35505288, 2022).
paronychia (continued). "Of note, paronychia is almost never seen with first generation EGFR–TKIs, erlotinib, and gefitinib." (PMID 25279350, 2014).
Alzheimer disease (61 papers, 2008 to 2025). A progressive, neurodegenerative disease characterized by loss of function and death of nerve cells in several areas of the brain leading to loss of cognitive function such as memory and language. "Recently, it has been inversely associated with dementia risk at midlife, and the EGFR gene has been implicated in Alzheimer’s disease." (PMID 38438772, 2024). "The frequencies of EGFR mutations were similar in Early-Ad cases of different pathological classes and advanced cases (AIS Noguchi type A: 56%, type B: 71%, MIA and Lepidic-Ad: 59%, Advanced-Ad cases: 65%)." (PMID 38102134, 2023). "Recent researches found that the Alzheimer’s disease (AD) is associated with abnormally phosphorylated tau and EGFR signaling in the neuron cells." (PMID 30312357, 2018). "Further, studies also indicate role of PS1 in trafficking and turnover of EGFR as well as perturbed endosomal-lysosomal trafficking in cell cycle control and Alzheimer disease and suggest potential pathogenic effects of elevated EGFR." (PMID 24628925, 2014). "In a recent study, EGFR has been suggested as a preferred target for treating amyloid-beta induced memory loss in Alzheimer's disease." (PMID 24688734, 2013). "Deficient signalling of the EGFR is associated with Alzheimer's disease." (PMID 39919333, 2025). "Further, TNS3 interacts with AD-related druggable genes EGF and HGF, which in turn interact with EGFR (eFigure-11), a gene that was recently implicated in Alzheimer’s disease through GWAS15 and itself shows strong potential as a dual drug target for cancer and AD68." (PMID 41404291, 2025). "Intriguingly, a recent large genome-wide association study (GWAS) has identified EGFR as one of the most significant novel risk genes for late onset Alzheimer’s disease (LOAD) raising the question of the possible participation of SHIP2 in EGFR function/turnover in AD." (PMID 38833073, 2024). "Furthermore, they administered several EGFR inhibitors (e.g., erlotinib and gefitinib) to transgenic fly and a mouse model of Alzheimer’s disease and found that the inhibitors prevented memory loss in both animal models." (PMID 33941241, 2021). "As EGFR is also involved in the development and in the maintenance of the nervous system, alteration in its signaling is associated with the onset of several neurological diseases, such as, for instance, Parkinson’s disease, Alzheimer’s disease and amyotrophic lateral sclerosis." (PMID 32806510, 2020). "Epidermal growth factor receptor (EGFR) was identified as a potential crucial receptor gene in Alzheimer’s disease (AD) and Parkinson’s disease (PD) comorbidity via bioinformatics analysis." (PMID 38894850, 2024). "EGFR, especially pEGFR, is upregulated after neuronal injury and in pathological conditions such as Parkinson’s, Huntington’s and Alzheimer disease, and amyotrophic lateral sclerosis (ALS)." (PMID 39000275, 2024). "Association of APOE, EGFR, and ACTB SNPs with Alzheimer’s disease under logistic regression analysis." (PMID 34956307, 2021). "EGFR is present in the cerebral cortex and hippocampal plaques of patients affected by Alzheimer’s disease." (PMID 32806510, 2020). "In the case of Alzheimer’s disease, EGFR targeting has been proposed to treat amyloid-β induced memory loss." (PMID 28792504, 2017). "MiR-128 regulates the formation of fear-extinction memory and reduces AKT signaling by repressing receptor tyrosine kinases EGFR and PDGFα; it is, also, deregulated in Alzheimer’s disease." (PMID 23056445, 2012). "EGFR mediates the EGF-induced chemotactic and chemokinetic migration of microglia, and EGFR signaling functions in several CNS disorders, such as ischemia, tuberous sclerosis, and Alzheimer’s disease, as well as after SCI." (PMID 22824323, 2012). "However, a clinical report showed intensive EGFR expression in the neurites in affected brain tissues of patients with Alzheimer disease (AD), suggesting an EGFR reactivation in response to insults." (PMID 40444141, 2025).
Alzheimer disease (continued). "Other UK Biobank affiliated researchers utilized scRNA-seq to support the role of EGFR in Alzheimer’s disease pathology and characterize the context of EGFR signaling that could be utilized for developing future targeted therapeutics for Alzheimer’s disease." (PMID 39777270, 2024). "Several membrane receptors, including EGFR, interact with amyloid β (Aβ), raising the possibility that erlotinib could have therapeutic effects on Alzheimer's disease (AD)." (PMID 39434878, 2024). "Rapid activation of EGFR signaling also occurs after several other CNS disorders, such as electrolytic lesions and entorhinal ablation, in the damaged brains of patients after stroke, and in those with Alzheimer’s disease." (PMID 22824323, 2012). "The KEGG pathways mainly involved Alzheimer’s disease (hsa05010), neuroactive ligand-receptor interaction (hsa04080), calcium signaling pathway (sa04020), pathways in cancer (hsa05200), serotonergic synapse (hsa04726), and EGFR tyrosine kinase inhibitor resistance (hsa01521)." (PMID 37895137, 2023). "Therefore, blocking EGFR activation in astrocytes could be beneficial for the treatment of neuroinflammation, which characterizes CNS neurodegenerative diseases including Alzheimer’s disease although this has still to be proved." (PMID 32806510, 2020). "In the pathway unification database, SRC, EGFR, MAPT, APP and PRKCA were identified as key molecules in the pathway of Alzheimer’s disease." (PMID 37010714, 2023). "We applied our computational framework to prioritize novel putative target genes for Alzheimer’s disease and successfully identified key genes that may serve as novel therapeutic targets (e.g., DLG4, EGFR, RAC1, SYK, PTK2B, SOCS1)." (PMID 33941241, 2021). "In Alzheimer’s disease (AD) patients, circPSEN1 is significantly up-regulated, promoting amyloid-β (Aβ) production by inhibiting miR-137 expression and activating the nuclear factor of activated T cells 1 (NFATC1) and epidermal growth factor receptor (EGFR) pathways." (PMID 40801613, 2025). "In addition, regarding neurodegenerative diseases (NDDs), several functions, including Huntington’s disease signaling (EGFR, MAPK1, PSMB3), neuroprotection by THOP1 in Alzheimer’s disease (AGT, MAPK1) and Parkinson’s signaling (MAPK1), were activated only in aged mice." (PMID 38590360, 2024). "Specifically, we hypothesized that EGFR signaling represents a potential avenue for enhancing NSPC activity in the context of the declining neurogenesis that occurs during normal aging and that is further accelerated in Alzheimer’s disease (AD)." (PMID 33841077, 2021).
cardiac hypertrophy (61 papers, 2009 to 2025). "EGFR loss in vascular smooth muscle cells and cardiomyocytes leads to arterial hypotension and cardiac hypertrophy." (PMID 33233425, 2020). "The aim of this study was to test if the novel EGFR inhibitors are able to attenuate Ang II‐induced cardiac hypertrophy both in vitro and in vivo and identify the underlying mechanism." (PMID 26762600, 2016). "The aim of this current study was to examine the role of EGFR in angiotensin II (Ang II)‐induced cardiac hypertrophy and identify the underlying molecular mechanisms." (PMID 26762600, 2016). "We previously reported that EGFR deficiency in all cardiac cell types (waved-2 mice) led to mild cardiac hypertrophy whereas the cardiomyocyte-specific decrease in EGFR activity (DN-EGFR mice) did not." (PMID 22291909, 2012). "Epidermal growth factor receptor (EGFR) is a member of receptor tyrosine kinase whose deficiency could worsen myocardial hypertrophy, cardiac dysfunction and arterial hypotension (Refs 68, 69)." (PMID 38525836, 2024). "Moreover, in a study of cardiac remodeling in subtotal nephrectomy-induced chronic kidney disease, MK-deficient mice had lessened ERK1/2, Akt and EGFR phosphorylation and alleviated cardiac hypertrophy." (PMID 36204583, 2022). "Although EGFR activation results in cardiac hypertrophy, whether β-arrestin-mediated transactivation of EGFR is associated with cardiac hypertrophy is unknown." (PMID 30538631, 2018). "Although enhancement of pro-apoptotic protein expression would not relay a prosurvival EGFR signal, Tef deletion in mice has been associated with enhanced cardiac hypertrophy and left ventricular dysfunction, thus EGFR-dependent maintenance of Tef expression may ultimately promote survival." (PMID 24901703, 2014). "EGFR also plays a critical role in bone marrow-derived cells; its deletion in these cells leads to cardiac hypertrophy, reduced capillary density, and impaired myocardial repair, indicating its importance in cardiac homeostasis and stress response." (PMID 40725470, 2025). "GRK2 also modulates other GPCRs and receptor tyrosine kinases (RTKs), such as the epidermal growth factor receptor (EGFR), influencing cardiac hypertrophy and survival pathways." (PMID 40001594, 2025). "HB-EGF and EGFR families are upregulated under pathological conditions such as cardiac hypertrophy or myocardial infarction." (PMID 38242884, 2024). "Another hypertrophic factor, Ubiquitin C-terminal hydrolase L1 (UCHL1) is related to fibrosis and has proven to deubiquitinate and stabilize the epidermal growth factor receptor (EGFR), promoting cardiac hypertrophy." (PMID 36860278, 2023). "Another study showed that GDF-15 blocks norepinephrine-induced myocardial hypertrophy through a pathway involving inhibition of the epidermal growth factor receptor transactivation." (PMID 37189644, 2023). "Jak-Stat Signaling: IL-6 pathway is activated in response to the IL-6 family of cytokines (IL-6, cardiotrophin 1, and leukemia inhibitor factor), cross-talks with the EGFR pathway, and is involved in cardiac hypertrophy." (PMID 36380187, 2022). "Altogether our data point that EGFR pathway activation is centrally involved in cardiac hypertrophy that rises from two very different mouse models." (PMID 36380187, 2022). "miRNAs are involved in the modulation of all three major components of AT1R signalling in cardiac hypertrophy, namely the canonical pathway, the EGFR transactivation pathway, and the inflammatory pathway." (PMID 33946230, 2021). "For both aldosterone/MR and the EGFR, a stimulatory effect on cardiac hypertrophy and remodeling has been demonstrated." (PMID 34168192, 2021). "Using transgenic flies, the authors showed how overexpression of the RTK EGFR led to cardiac hypertrophy and how this effect was prevented by blocking ERK activation." (PMID 33923899, 2021).
cardiac hypertrophy (continued). "Recently, it was reported that UCH-L1 promotes cardiac hypertrophy through deubiquitination and stabilization of EGFR and activation of EGFR downstream mediators, including Akt." (PMID 34745437, 2021). "They reported that Ang II-induced cardiac hypertrophy, fibrosis and remodeling was mediated via enhanced signaling through a Src-dependent EGFR/AKT pathway." (PMID 34408653, 2021). "In vitro experiments indicate that EGFR activation promotes α1-adrenergic receptor- and angiotensin II-induced cardiac hypertrophy." (PMID 32831633, 2020). "It has been previously demonstrated that EGFR agonists can induce cardiac hypertrophy and remodeling through the activation of metalloproteinases that cleave and release EGFR ligands." (PMID 31534849, 2019). "It has been reported that up-regulation of GDF15 negatively regulated norepinephrine-induced myocardial hypertrophy by inhibiting epidermal growth factor receptor (EGFR) transactivation." (PMID 31498116, 2019). "Increased expression of CTGF promotes the development of cellular hypertrophy, while a decrease in EGFR reduces the interaction with CTGF to release more CTGF to promote the development of cardiac hypertrophy." (PMID 31200637, 2019). "This provides the possibility for ERK1/2 to coordinate GPCR and EGFR signaling during the cardiac hypertrophy." (PMID 31200637, 2019). "We found that high expression of CTGF and low expression of EGFR were regulated by ERK1/2 signaling pathway during the cardiac hypertrophy induced by Ang-II stimulation." (PMID 31200637, 2019). "EGFR is a receptor tyrosine kinase and EGFR activation has been shown to play an important role in the development of cardiac hypertrophy." (PMID 29221204, 2017). "Inhibition of guanine nucleotide-binding protein subunit alpha-11, 14, and 15 (GNA-11,14,15), along with GNAQ, inhibits 1-phosphatidylinositol 4,5-bisphosphate phosphodiesterase beta-1, 2, 3, and 4, thus reducing cardiac hypertrophy through EGFR blockade." (PMID 28649439, 2017). "Inhibition of HB-EGF shedding attenuates cardiac hypertrophy induced by GPCR agonists indicating a key role of EGFR activation in the process." (PMID 29221204, 2017). "In the current study, we demonstrate that EGFR inhibitors have protective effects against Ang II‐induced cardiac hypertrophy, validating a critical role of EGFR in mediating cardiac hypertrophy." (PMID 26762600, 2016). "In conclusion, we demonstrate that EGFR play a key role in cardiac hypertrophy and EGFR inhibition by either small‐molecule inhibitors or genetic silencing can protect against Ang II‐induced cardiac hypertrophy." (PMID 26762600, 2016). "Among these signaling molecules, ERK1/2 is known to be involved in cardiac hypertrophy-induced by both EGFR and PARs." (PMID 26823023, 2016). "In mice cardiac hypertrophy, the apoptosis and fibrosis of cardiac myocytes were attenuated when the EGFR transactivation was diminished." (PMID 26550019, 2015). "Mutation of the conserved YIPP motif in the C terminus of AT1-R, resulted in diminished EGFR transactivation and cardiac hypertrophy in Tg-Y319F mice." (PMID 24699426, 2014). "AngII-dependent cardiac hypertrophy requires cardiac EGFR activation, and antisense to EGFR decreases left ventricular hypertrophy in young spontaneously hypertensive rats." (PMID 24132149, 2013). "AngII-induced cardiac hypertrophy is thus EGFR-dependent whereas that induced by aldosterone/salt is EGFR-independent." (PMID 22291909, 2012). "We thus extended treatment duration (two more weeks) to induce cardiac hypertrophy in CT mice and get a more robust conclusion about the role of EGFR in cardiac effects of aldosterone." (PMID 22291909, 2012). "In contrast, NAS induce cardiac hypertrophy even when EGFR activation is defective in cardiomyocytes." (PMID 22291909, 2012). "For example, epidermal growth factor receptor (EGFR) phosphorylation is known to be involved in the development of pressure overload-induced cardiac hypertrophy." (PMID 21080942, 2010).